TFAP2A (transcription factor AP-2 alpha)
Diseases named in the same sentence as TFAP2A in open-access papers (continued):
Sharing a sentence is not in itself a finding about the gene and the disease.
oral squamous cell carcinoma (2 papers, 2023 to 2025). "RELA was found directly interact with the cis-regulatory region of TFAP2A, to upregulate the TFAP2A expression in the oral squamous cell carcinoma (OSCC)." (PMID 37291585, 2023). "A study had shown that in oral squamous cell carcinoma (OSCC), TFAP2A was elevated, and NFκB (RelA) enhanced OSCC progression via regulating TFAP2A-Wnt/β-catenin signaling." (PMID 40813717, 2025). "TFAP2A binds to the promoters of tectonic family member 1 (TCTN1) and amyloid precursor protein (APP)to induce malignancy (proliferative, migratory and invasive capacity) in the oral squamous cell carcinoma (OSCC)." (PMID 37291585, 2023).
pancreatic adenocarcinoma (2 papers, 2023 to 2024). "In pancreatic adenocarcinoma, TFAP2A interacts with the mucin 4 (MUC4) promoter to suppress MUC4 expression, which prevents cell proliferation and invasion." (PMID 37291585, 2023). "In lung squamous cell carcinoma (LUSC) and pancreatic adenocarcinoma (PAAD), TFAP2A-induced SLC2A1-AS1 (solute carrier family 2 member 1-antisense RNA 1) promotes tumor malignancy." (PMID 37291585, 2023).
prostate adenocarcinoma (2 papers, 2023). "An early study discovered that the presence of TFAP2A was associated with normal luminal differentiation of the prostate and that TFAP2A loss may be involved in the early occurrence of prostate adenocarcinoma." (PMID 37291585, 2023).
psoriasis (2 papers, 2011 to 2025). An autoimmune condition characterized by red, well-delineated plaques with silvery scales that are usually on the extensor surfaces and scalp. "Several TFs, including TFAP2A, have been identified in the skin samples of psoriasis patients and have been associated with the development of skin lesions in psoriasis." (PMID 40078960, 2025). "The resulting group of genes includednegative regulators of inflammation, such as the psoriasis susceptibility geneTNFAIP3 and theNotch ligand jagged 2, and also genes regulating epidermal differentiation,such as the transcription factor AP2-α (TFAP2A), and the apoptosis-inducing FASmolecule." (PMID 21611195, 2011).
retinoblastoma (2 papers, 2021 to 2025). A malignant tumor that originates in the nuclear layer of the retina. "In this context, recent studies have further validated Transcription Factor Activating Enhancer-Binding Protein 2 Alpha (TFAP2A) promoter methylation as a highly specific biomarker in aqueous humor (92.7% diagnostic accuracy) for distinguishing retinoblastoma from benign retinal conditions." (PMID 41150792, 2025). "Also, TFAP2A and cfDNA were found to be hypermethylated and the study states that the methylation levels of these two molecules could be diagnostic biomarkers of retinoblastoma." (PMID 41150792, 2025).
spina bifida (2 papers, 2010 to 2024). A congenital neural tube defect in which vertebrae are not fully formed. "Deletion of a conditional allele of Grhl3 using a mouse line expressing Cre recombinase expressed from Tfap2a regulatory elements recapitulated the spina bifida observed in constitutive Grhl3-null animals." (PMID 39296075, 2024). "Deletion of Grhl3 expression in this cell population using a Tfap2a-Cre transgene recapitulates the spina bifida observed in Grhl3-null animals." (PMID 39296075, 2024). "The purpose of this study is to evaluate the potential association between variations among human CITED2, CREBBP, EP300, TFAP2A, CARM1 and ALX1 genes and the risk for spina bifida." (PMID 20932315, 2010). "We have observed modest associations with risk of spina bifida in CITED2, EP300, CREBBP, TFAP2A and CARM1 genes but not ALX1 gene." (PMID 20932315, 2010).
thyroid cancer (2 papers, 2010 to 2017). "Previous studies reported that TFAP2A was upregulated in thyroid cancer compared to normal thyroid." (PMID 29383121, 2017).
acne rosacea (1 paper, 2025). "However, the risk allele substantially enhances TFAP2A DNA binding, consistent with a model in which the rs1264326 daSNV enhances TFAP2A promoter binding to alter expression of DDR1 and PSORS1C1 pro-inflammatory genes and drive risk for acne rosacea." (PMID 40998781, 2025).
acute lymphoblastic leukemia (1 paper, 2015). Leukemia with an acute onset, characterized by the presence of lymphoblasts in the bone marrow and the peripheral blood. "Transcription factor AP-2 alpha (TFAP2A) and Early B-Cell Factor 2 (EBF2) were identified as epigenetic molecular markers in Acute lymphoblastic leukemia (ALL) and CML-BP." (PMID 25575817, 2015).
anencephaly (1 paper, 2023). A rare neural tube defect during pregnancy, resulting in the absence of a large portion of the brain and skull in the fetus. "Earlier researchers found that TFAP2A-deficient mice suffered from anomalies, such as anencephaly, congenital heart disease, and body-wall defects." (PMID 36833449, 2023).
aortic aneurysm (1 paper, 2025). A ruptured aneurysm located in the wall of the proximal portion of the descending aorta proceeding from the arch of the aorta. "Taken together, these findings demonstrated that HINT1 promotes VSMC phenotypic switching and aggravates aortic aneurysm in an ITGA6-dependent manner through direct interaction with TFAP2A, which is responsible for the transcriptional activation of ITGA6." (PMID 40198125, 2025).
Arthritis (1 paper, 2019). Inflammation of a joint. "Taken together, we proposed the up-regulated TFAP2A in OA synovial tissue may represent higher degree of inflammation in OA, and TFAP2A may be a novel target for anti-inflammatory therapy in arthritis." (PMID 31523167, 2019).
bladder tumors (1 paper, 2020). "Furthermore, our immunohistochemical data is in good agreement with previous reports that demonstrate high levels of TFAP2A, P63, and TRIM29 within basal bladder tumors that have areas of squamous differentiation." (PMID 32822399, 2020).
brain cancer (1 paper, 2025). A primary or metastatic malignant neoplasm affecting the brain. "Among the other transcription factors that we found among colon transcriptomics features Irx2, Pou4f1, Pou6f1, Tfap2a, Ctdp1, and Msx1 are known to be involved in neuronal development or closely related processes 31–37, and Fubp1 in brain cancer." (PMID 40791429, 2025).
congenital glaucoma (1 paper, 2025). "This is consistent with the identification of a TFAP2A splicing variant (c.1025+2T>A) in a patient with Peters anomaly associated with congenital glaucoma." (PMID 41011222, 2025).
depression (1 paper, 2024). "Of note, differential methylation of TFAP2A has been described in a twin study of early-onset major depression disorder." (PMID 38256187, 2024). "Five of these TFs, namely ETS1, TFAP2A, NFKB2, CTCF, and RELA, are significantly deregulated in the blood samples of depression patients compared to controls (GSE217811 and GSE23848)." (PMID 38256187, 2024).
diffuse large B-cell lymphoma (1 paper, 2024). "The data suggested that TFAP2A positively regulated “GPCR LIGAND BINDING” signaling pathways in Adrenocortical carcinoma (ACC), COAD, Lymphoid neoplasm diffuse large B-cell lymphoma (DLBC), OV, and THCA." (PMID 38265973, 2024).
endometrial cancer (1 paper, 2020). Primary or metastatic malignant neoplasm involving the endometrium (mucous membrane that lines the endometrial cavity). "Particularly, expression of TFAP2A, MMP12, TOP2A, ASPM and CFB were higher in endometrial cancer relative to normal tissues." (PMID 32555395, 2020).
epilepsy (1 paper, 2023). A brain disorder characterized by episodes of abnormally increased neuronal discharge resulting in transient episodes of sensory or motor neurological dysfunction, or psychic dysfunction. "Next, the upstream transcription factor- transcription factor activating enhancer binding protein 2 α (TFAP2A), which is highly matched with syntabulin and notably related to epilepsy, was predicted by JASPAR software." (PMID 37349285, 2023). "To examine the role of TFAP2A in epilepsy, we detected increased TFAP2A expression in the hippocampus of KA model mice." (PMID 37349285, 2023). "According to JASPAR software prediction and verification, we found that syntabulin is regulated by transcription factor TFAP2A in epilepsy." (PMID 37349285, 2023). "These evidences suggest that TFAP2A regulates syntabulin expression in epilepsy and STX1B expression in synaptosomes, and affects neural excitability." (PMID 37349285, 2023).
gestational diabetes mellitus (1 paper, 2022). "Tfap2a can be induced by factors such as retinoic acid, UVA radiation, and singlet oxygen, and there is a high level of the TFAP2A gene in patients suffering from gestational diabetes mellitus and type 1 diabetes." (PMID 36430853, 2022).
head and neck carcinoma (1 paper, 2024). A carcinoma that arises from the head and neck region. "Among the 60 DETGs, genes such as TFAP2A, CLSPN, RASEF, HIST1H3H, AKT3, and ITPR1 were associated with metastasis to secondary sites, including the lungs, and with head and neck carcinoma." (PMID 39095857, 2024).
Hypercholesterolemia (1 paper, 2022). An increased concentration of cholesterol in the blood. "The SNP rs569210477 variant on the TFAP2A gene was associated with a higher risk of hypercholesterolemia in young men." (PMID 36233190, 2022).
Hypertelorism (1 paper, 2025). Interpupillary distance more than 2 SD above the mean (alternatively, the appearance of an increased interpupillary distance or widely spaced eyes). "Among them, mice with a deficiency for Fgfr1, Fgfr2, Kif3a, Kras, Ptch1, Rreb1, Sos1, and Tfap2a show excessive proliferation during midfacial development, resulting in hypertelorism, suggesting that mimics of miR-383-3p and miR-6951-3p activate cell proliferation through suppression of these genes." (PMID 40787625, 2025).
idiopathic dilated cardiomyopathy (1 paper, 2024). Decreased function of the heart associated with cardiac enlargement and congestive heart failure, of unknown cause. "This is different from our finding of reduced Tfap2a transcript levels in HFpEF mice, and we speculate that this may be due to the large differences in pathophysiologic mechanisms between HFpEF and idiopathic dilated cardiomyopathy." (PMID 38402404, 2024).
lipid metabolism disorder (1 paper, 2025). "In this study, we systematically investigated the specific function of Tfap2a in fibrosis and inflammation- or lipid metabolism disorder-related HCC by conditionally knocking out Tfap2a in three types of cells from mouse liver combined with DEN/CCl4 induction." (PMID 40180937, 2025).
liver steatosis (1 paper, 2025). "Here, we investigated the importance of AP-2α in liver steatosis and inflammation by establishing Tfap2a-knockout mouse models in hepatocytes and macrophages." (PMID 40180937, 2025). "Taken together, hepatocyte- or macrophage-specific deletion of Tfap2a promotes hepatic steatosis, fibrosis, and the development of HCC." (PMID 40180937, 2025). "Conditional knockout of Tfap2a was able to promote hepatic steatosis in Tfap2aΔHep and Tfap2aΔMΦ mice, but not in Tfap2aΔHSC mice fed with normal chow." (PMID 40180937, 2025).
malaria (1 paper, 2023). Malaria is a serious and sometimes fatal disease caused by a parasite that commonly infects a certain type of mosquito which feeds on humans. "Previous studies show that TFAP2A (AP2) regulates the transcription of IFN-γ Receptor 1 (IFNGR1), and that elevated IFN-γ production is protective against infection with malaria." (PMID 37704951, 2023).
metastasis (1 paper, 2025). The spread or migration of cancer cells from one part of the body (where they first appeared) to another. "Among them, TFAP2A was found to be associated with liver metastasis in PDAC." (PMID 40727938, 2025).
metastatic melanoma (1 paper, 2023). A melanoma that has spread from its primary site to another anatomic site. "In metastatic melanoma cells, decreased TFAP2A changes the binding ratio of TFAP2A/SP1 on the protease-activated receptor-1 (PAR1) promoter, which results in overexpression of PAR1 and promotes tumor oncogenesis and malignancy." (PMID 37291585, 2023).
monocytic leukemia (1 paper, 2011). "We also identified PWMs for transcription factor activating enhancer binding protein 2 (TFAP2A), which is known to activate ADM expression in monocytic leukemia cells, for TFAP4 and for transcriptional activators of the GATA binding protein family." (PMID 22039494, 2011).
mood disorder (1 paper, 2024). A cognitive disorder a disturbance in which the person's mood is hypothesized to be the main underlying feature. "Furthermore, TFAP2A is among the TFs associated with mood disorders in general and MDD in particular in humans." (PMID 38256187, 2024).
optic nerve coloboma (1 paper, 2024). "A TFAP2A missense variant was identified in a patient affected by chorioretinal and optic nerve coloboma (A153)." (PMID 38459225, 2024).
osteosarcoma (1 paper, 2023). A usually aggressive malignant bone-forming mesenchymal neoplasm, predominantly affecting adolescents and young adults. "Besides these, we found KLF4, STAT3, BCL6, TFAP2A, and TFAP4 as potential drivers of osteosarcoma metastasis." (PMID 37938582, 2023).
ovarian serous cystadenocarcinoma (1 paper, 2024). A malignant serous cystic epithelial neoplasm arising from the ovary. "Results indicated that TFAP2A was positively associated with the HR in KIRC and KIRP yet negatively associated with Ovarian serous cystadenocarcinoma (OV) and UVM, which would be further studied." (PMID 38265973, 2024).
ovarian tumours (1 paper, 2019). "Association analysis within the group of ovarian tumours showed that the level of TFAP2A transcripts correlated positively with CGB3–9 gene expression (R = 0.67)." (PMID 31362717, 2019).
periodontitis (1 paper, 2022). An acute or chronic inflammatory process that affects the tissues that surround and support the teeth. "On the contrary, GDF15, SCD and TFAP2A had lower sensitivity in predicting periodontitis with T2DM, with AUCs of 0.54, 0.60 and 0.66, respectively." (PMID 36248844, 2022).
schizophrenia (1 paper, 2021). A major psychotic disorder characterized by abnormalities in the perception or expression of reality. "TFAP2A knockout mice died of cranioabdominal schizophrenia during the perinatal period, with severe malformations of the face, skull, sensory organs and cranial ganglia." (PMID 33717678, 2021).
schwannoma (1 paper, 2013). A benign, usually encapsulated slow growing tumor composed of Schwann cells. "Both states, as well as schwannomas, exclusively overexpress α4-integrin (ITGA4, 1.8-fold, p= 0.003), AP2a (TFAP2A, 1.41-fold, p= 0.009) and Ncad (CDH2, 4.5-fold, p=5.42e-4)." (PMID 23354516, 2013).
Stomach Cancer (1 paper, 2018). "Collectively, these findings suggested that ZNF471 is a novel gastric tumor suppressor which functions by transcriptional inhibition of its oncogenic targets, TFAP2A and PLS3." (PMID 29610526, 2018).
systemic sclerosis (1 paper, 2023). A chronic disorder, possibly autoimmune, marked by excessive production of collagen which results in hardening and thickening of body tissues.
Tetralogy of Fallot (1 paper, 2020). A congenital cardiac malformation comprising pulmonary stenosis, overriding aorta, ventricular septum defect, and right ventricular hypertrophy. "Additionally, TFAP2A has been associated with the negative regulation of the T-box gene, TBX20, the expression of which is increased in atrial and ventricular biopsies of patients with Tetralogy of Fallot." (PMID 32717817, 2020).
thyroid tumor (1 paper, 2017). A benign or malignant neoplasm affecting the thyroid gland. "Databases such as TCGA report that 1-2% of thyroid tumors display overexpression of TFAP2A, though there does not appear to be any obvious differences in survival for this group." (PMID 29383121, 2017).
type 2 diabetes (1 paper, 2022). "Levels of Tfap2a in GV oocytes of mice suffering from type 2 diabetes increased considerably." (PMID 36430853, 2022).
uveal melanoma (1 paper, 2023). A melanoma derived from melanocytes of the uveal tract. "Importantly, analyses of TCGA data confirmed that high expression of PAX3, SOX10, MITF and TFAP2A are defining features of uveal melanoma patient samples and such TFs have been validated as selective cancer dependencies in UM cell lines by large-scale functional genomics screens." (PMID 37400441, 2023).
van der Woude syndrome (1 paper, 2021). Van der Woude syndrome (VWS) is a rare congenital genetic dysmorphic syndrome characterized by paramedian lower-lip fistulae, cleft lip with or without cleft palate, or isolated cleft palate. "Mutations in the TFAP2A gene can also cause branching eye and face syndrome, which has overlapping features with Van der Woude syndrome, such as orofacial cracks." (PMID 33717678, 2021).
vitiligo (1 paper, 2025). Generalized well circumscribed patches of leukoderma that are generally distributed over symmetric body locations and is due to autoimmune destruction of melanocytes. "The role of TFAP2A in vitiligo needs further exploration and experimental evidence." (PMID 40078960, 2025).